LHX8 (LIM homeobox 8)
Description:
Transcription factor involved in differentiation of certain neurons and mesenchymal cells.
Synonyms: Lhx7
Tractability: No criterion of Open Targets' tractability assessment is met for any kind of drug.
Gene: Protein-coding gene on chromosome 1 (75,128,434 to 75,161,533, forward strand). Ensembl gene ENSG00000162624.
Subcellular location: Nucleus
Subcellular location (Human Protein Atlas): Nucleoli; Nucleoplasm; Cytosol
Gene Ontology:
Molecular function: protein binding; sequence-specific double-stranded DNA binding; DNA-binding transcription factor activity, RNA polymerase II-specific; RNA polymerase II transcription regulatory region sequence-specific DNA binding; DNA binding; sequence-specific DNA binding
Biological process: forebrain neuron development; neuron differentiation; regulation of transcription by RNA polymerase II; regulation of DNA-templated transcription; response to ethanol
Cellular component: chromatin; nucleus
Genetic constraint (gnomAD): Loss-of-function variants: 11 observed, 35.1 expected, observed/expected ratio (o/e) 0.31, 90% interval 0.2 to 0.52. The upper end of that interval is the gene's LOEUF score, 0.52, which puts it in group 2 of 6, group 1 being the genes least tolerant of losing a copy. Missense variants: 328 observed, 431.78 expected, observed/expected ratio (o/e) 0.76, 90% interval 0.69 to 0.83. Synonymous variants: 173 observed, 165.09 expected, observed/expected ratio (o/e) 1.05, 90% interval 0.93 to 1.19.
Homologues: Orthologues: chimpanzee LHX8 (100% identical), macaque LHX8 (99% identical), rabbit LHX8 (99% identical), dog LHX8 (98% identical), pig LHX8 (98% identical), mouse Lhx8 (96% identical), rat Lhx8 (92% identical), guinea pig LHX8 (86% identical), tropical clawed frog lhx8 (86% identical), zebrafish lhx8a (71% identical), zebrafish lhx8b (47% identical). Paralogues in human: LHX6 (58% identical), ZFHX3 (33% identical), ZFHX4 (32% identical), LHX9 (31% identical), LMX1B (31% identical), LHX2 (30% identical), LMX1A (28% identical), LHX5 (27% identical), LHX1 (26% identical), LHX4 (26% identical), LHX3 (25% identical), ZFHX2 (25% identical), and 8 more.
Diseases named in the same sentence as LHX8 in open-access papers:
LHX8 is named in the same sentence as 34 diseases in open-access papers, as found by Europe PMC text mining. Sharing a sentence is not in itself a finding about the gene and the disease. The quoted sentences say what the papers report.
cervical cancer (6 papers, 2018 to 2025). A primary or metastatic malignant neoplasm involving the cervix. "Particularly for DNA methylation markers ASCL1 and LHX8, they were shown to yield a high sensitivity for cervical cancer detection, constituting a possible direct triage method for cancerous lesions in HPV-positive women." (PMID 40137778, 2025). "Methylation levels of several host cell genes, including ASCL1, LHX8, and ST6GALNAC5, increase with the severity of the underlying cervical disease and are particularly high in cervical scrapes of women with cervical cancer." (PMID 30360578, 2018). "At a threshold corresponding to 75% specificity, CIN3+ sensitivity was 72.1% for ASCL1 and 73.8% for LHX8 and all samples from women with cervical cancer scored positive for these two markers." (PMID 30101434, 2018). "This study reports on primary DNA methylation analysis of host cell genes ASCL1, LHX8 or ST6GALNAC5 for the detection of cervical cancer and CIN3 in cervical scrapes from WLHIV." (PMID 30101434, 2018). "They identified 6 genes as the best candidate methylated biomarkers of cervical cancer progression (RGS7, LHX8, ST6GALNAC5, TBX20, KCNA3 and ZSCAN18)." (PMID 34882728, 2021). "Urine samples (27 controls, 30 CIN3 and 17 cervical cancer) were processed into 3 fractions and tested for 5 methylation markers (ASCL1, GHSR, LHX8, SST, ZIC1)." (PMID 32171935, 2020). "Methylation of ASCL1, LHX8, and ST6GALNAC5, as found in cervical cancer, has also been detected in oral cancer (ASCL1), colorectal cancer (ASCL1 and ST6GALNAC5), and breast cancer (LHX8), suggesting a tumour suppressive role of these genes in these cancers." (PMID 30360578, 2018). "To further evaluate the performance of ASCL1, LHX8 and ST6GALNAC5 to detect CIN3 and cervical cancer, we calculated the positivity rates in the referral population for each histology subgroup at the fixed thresholds of 75% and 80% specificity." (PMID 30101434, 2018). "This indicates that single methylation marker analysis of ASCL1 or LHX8 would be an interesting primary cervical screening tool in WLHIV in low‐resource settings, as it detects the majority of CIN3 lesions that need treatment and provides a high reassurance against cervical cancer." (PMID 30101434, 2018).
cleft palate (6 papers, 2006 to 2025). Cleft palate is a fissure type embryopathy that affects the soft and hard palate to varying degrees. "Among these genes, ablation or mutation of Alx3, Lhx8, Pax3, Pitx1, Shox2, and Zeb2 induces cleft palates in humans and/or mice." (PMID 27329940, 2016). "Except for DISP1, all these genes have been associated with cleft palate in mouse models, whereas only LHX8 and GAD1 have been associated with cleft palate disorders in humans." (PMID 19557186, 2009). "Additionally, a targeted Lhx8 mutation in mice caused cleft palate in around 60% of animals." (PMID 32571211, 2020). "LHX8 and FOXE1 are transcription factors essential for craniofacial development and have been linked to cleft palate." (PMID 41075272, 2025).
Infertility (6 papers, 2015 to 2026). "Recent WES data in a cohort of women with infertility and oocyte maturation arrest, however, report the identification of 5 novel heterozygous loss of function LHX8 variants that produce truncated proteins." (PMID 39391877, 2024). "Conditional deficiency of either Sohlh1 or Lhx8 in the oocytes of primordial follicles causes massive primordial oocyte activation and postnatal oocyte depletion leading to infertility in mice." (PMID 37194006, 2023). "The deletion of lhx8 leads to the loss of oocytes in the ovaries and the infertility of female mice." (PMID 33920938, 2021). "We previously reported that global knockout of Lhx8 causes infertility and loss of oocytes by postnatal day 7 (PD7)." (PMID 26076587, 2015). "CONCLUSIONS: These findings expand the phenotypic spectrum of LHX8 related infertility and provide mechanistic evidence that partial reduction of LHX8 activity compromises oocyte quality." (PMID 41566502, 2026). "Unlike PTEN-mediated pathways, whose actions are stage-specific and confined to PFA, Lhx8 deletion in primary oocytes disrupts follicle growth beyond primary oocytes and results in infertility." (PMID 26076587, 2015). "Our studies show that postnatal inactivation of Lhx8 within oocytes of primordial follicles leads to massive oocyte activation, decoupling of oocyte activation from somatic cell transformation, oocyte death, and infertility." (PMID 26076587, 2015). "Studies in mouse indicate that NOBOX, SOHLH1/SOHLH2 and LHX8 are co-expressed and cross-regulate each other, either directly or indirectly, thus controlling oocyte development during early follicular progression and therefore their mis-regulation leads to infertility." (PMID 39391877, 2024).
cervical disease (3 papers, 2018 to 2023). "The methylation levels of ASCL1 and LHX8 in HPV-positive self-collected samples increased with the severity of underlying cervical disease (Kruskal–Wallis omnibus test, both P values <0.0001)." (PMID 37100874, 2023). "Secondly, we investigated DNA hypermethylation of host cell genes ASCL1, LHX8, and ST6GALNAC5, as markers of advanced cervical disease, in relation to type-specific HPV infection." (PMID 30360578, 2018). "Differences across cervical disease categories in methylation levels of ASCL1, LHX8 and ST6GALNAC5 were evaluated in the two South African study cohorts combined." (PMID 30101434, 2018). "Hypermethylation levels of ASCL1,LHX8 and ST6GALNAC5 increased with severity of cervical disease." (PMID 30101434, 2018).
cervical intraepithelial neoplasia (2 papers, 2018 to 2021). "Significantly elevated levels were observed for GHSR and LHX8 in relation to high-grade cervical intraepithelial neoplasia (CIN2 +; n = 33), with area under de curve values of 0.80 (95% Confidence Interval (CI) 0.59–0.92) and 0.76 (95% CI 0.58–0.89), respectively." (PMID 33846517, 2021).
hepatocellular carcinoma (2 papers, 2020 to 2022). A malignant tumor that arises from hepatocytes. "Cluster 3 was enriched for LHX8 and FEV as well as DBX2, which is differentially expressed in hepatocellular carcinoma." (PMID 36404344, 2022).
Obesity (2 papers, 2020 to 2023). Accumulation of substantial excess body fat. "Assessing UCP1 and thermogenic gene products (e.g., MyoD1, LHX8, DIO2, PPARGC1A) in tissue materials removed during elective surgery may be used to predict obesity risk and initiate interventions to mitigate further adipose tissue expansion at an early stage." (PMID 38069028, 2023). "As obesity led to an increase in the number of atretic follicles, we wondered if this increase was induced by the abnormal expressions of the genes BMP4, GDF9, or LHX8 that play key roles during ovarian follicular development." (PMID 33282873, 2020).
ovarian failure (2 papers, 2015 to 2023). "Previously, we discovered that global knockouts of germ cell-specific transcriptional co-regulators Sohlh1, Sohlh2, Lhx8, and Nobox, cause rapid oocyte loss and ovarian failure." (PMID 26076587, 2015). "Based on this model, a loss-of-function mutation occurring in LNC1845 might lower the expression of LHX8 during human folliculogenesis and might lead to premature ovarian insufficiency." (PMID 36602025, 2023).
adrenal tumors (1 paper, 2022). "They assessed in the perirenal region of PPGL higher expression of UCP1, CIDEA, ELOVL3, EBF3, FBXO31 and LHX8, but not TNFSRF9, TBX1 or TMEM26, in comparison with seven subjects with non-functional adrenal tumors." (PMID 35327387, 2022).
anal carcinoma (1 paper, 2021). "A cross‐sectional series of 176 tissue samples of anal cancer, AIN3, AIN2, AIN1 and control biopsies obtained in HIV‐negative women and men was tested for six methylation markers (ASCL1, LHX8, SST, WDR17, ZIC1 and ZNF582)." (PMID 33580586, 2021).
diabetic neuropathy (1 paper, 2025). A chronic, pathological complication associated with diabetes mellitus, where nerve damages are incurred due to diabetic microvascular injury involving small blood vessels that supply these nerves, resulting in peripheral and/or autonomic nerve dysfunction. "We also saw a signal at gene level with LHX8 and TCF7L2 and neuropathic pain in diabetic neuropathy." (PMID 39471050, 2025).
female infertility (1 paper, 2023). Diminished or absent ability of a female to achieve conception. "By using the strategy, LHX8 and KPNA7 variants were identified to cause female infertility." (PMID 37052235, 2023).
Hypertension (1 paper, 2013). The presence of chronic increased pressure in the systemic arterial system. "Therefore, the similarities between the clinical features of PHAII and the phenotypes of Lhx8 knockdown or knockout mice strongly suggest that the WNK-Lhx8 pathway is involved in the pathogenesis of PHAII, aside from hypertension." (PMID 23383144, 2013).
neuroblastoma (1 paper, 2015). Neuroblastoma (NB) is the most common solid, extracranial childhood tumor. "Overexpression of LHX8 was sufficient to differentiate rat hippocampal neural stem cells or newborn neurons into cholinergic neuron types and induced expression of cholinergic markers in a human neuroblastoma cell line." (PMID 26305787, 2015).
schizophrenia (1 paper, 2024). A major psychotic disorder characterized by abnormalities in the perception or expression of reality. "Our finding that a population of developing LHX8-positive neurons of the MGE is also enriched for genetic association with schizophrenia suggests a role for cholinergic neuron development in later susceptibility to the condition." (PMID 38869145, 2024).
Tourette syndrome (1 paper, 2022). A neurologic disorder caused by defective metabolism of the neurotransmitters in the brain. "Moreover, a decrease in both GABAergic and cholinergic interneurons in the ventral telencephalon has been reported in Tourette Syndrome, suggesting LHX6 and LHX8 correlation with Tourette Syndrome due to their role in GABAergic and cholinergic interneuron specification in the striatum." (PMID 35546872, 2022).
cancer (4 papers, 2018 to 2021). A tumor composed of atypical neoplastic, often pleomorphic cells that invade other tissues. "Genes in PE‐Sor that have not been as strongly linked to cancer (COL25A1 and LHX8) did not change model accuracy to the same extent (<10%) when removed." (PMID 34766125, 2020).
lip (1 paper, 2025). "Novel loci include those mapping to LHX8 and TSBP1 (combined clefts), ARHGEF18 and ARHGEF19 (cleft lip with/without palate), FBN2 (cleft lip only), SLC35B3 (cleft palate only), CASC20 (Pierre Robin Sequence) and CHRM2 (non-syndromic cleft palate only)." (PMID 41075272, 2025).
nervous system disease (1 paper, 2021). "In the present study, we found that some genes of benefit to nervous system disease were activated (such as Lhx8, GPR88, RGS9, CD4, DRD2, RXRG, and Syt6), following the increase in the number of cholinergic and GABAergic neurons in the HSHF-diet offspring." (PMID 33819195, 2021). "As the offspring became older (16 months of age), we found that some genes of benefit to nervous system disease were activated, such as Lhx8, GPR88, RGS9, CD4, DRD2, RXRG, and Syt6, following the increase in the number of cholinergic and GABAergic neurons." (PMID 33819195, 2021). "When the offspring grew older (16 months), we found that some genes of benefit against nervous system disease were activated, such as Lhx8, GPR88, RGS9, CD4, DRD2, RXRG, and Syt6, and the expression of cholinergic and GABAergic neurons biomarker protein increased." (PMID 33819195, 2021).
LHX8 also shares sentences with these, for which no sentence is quoted: tumour (3 papers); orofacial cleft (2); adenomyosis (1); alcohol use disorder (1); breast carcinoma (1); colorectal cancer (1); diabetes (1); gestational diabetes (1); Hypergonadotropic hypogonadism (1); neurodevelopmental disorder (1); oral cancer (1); osteoarthritis (1); pancreatic cancers (1); prostate tumors (1); van der Woude syndrome (1).